SHANK3 (SH3 and multiple ankyrin repeat domains 3)
Diseases named in the same sentence as SHANK3 in open-access papers (continued):
Sharing a sentence is not in itself a finding about the gene and the disease.
neurodevelopmental disorder (74 papers, 2009 to 2026). A behavioral and cognitive disorder with onset during the developmental period that involves impaired or aberrant development of intellectual, motor, or social functions. "Phelan–McDermid syndrome (PMS) is a neurodevelopmental disorder, caused by haploinsufficiency of the SHANK3 gene." (PMID 40102980, 2025). "Phelan-McDermid syndrome (PMS) is a neurodevelopmental disorder associated with deletions or mutations on chromosomes 22q13.2 to 22q13.33 and haploinsufficiency of the SHANK3 gene." (PMID 40600073, 2025). "Phelan–McDermid syndrome (PMS; #MIM: 606232) is a rare neurodevelopmental disorder primarily caused by the haploinsufficiency of the SHANK3 gene, most often due to deletions encompassing the gene or single nucleotide variants within it." (PMID 40429797, 2025). "PMS is a neurodevelopmental disorder caused by haploinsufficiency of the SHANK3 gene, resulting either from deletions at 22q13.33 or from pathogenic or likely pathogenic variants." (PMID 40429797, 2025). "PMS is a rare neurodevelopmental disorder caused by deletions or mutations in chromosome 22q13.33, leading to SHANK3 haploinsufficiency." (PMID 40600073, 2025). "Mutations or deletions in the SHANK3 gene are linked to neurodevelopmental disorders, including ASD and striatal dysfunctions." (PMID 39595015, 2024). "It is suggested that early swimming exercise has a positive effect on Shank3 gene‐deficient rats, which provides a new therapeutic strategy for the prevention and recovery of neurodevelopmental disorders." (PMID 36221783, 2023). "SHANK3, which is located at the terminal end of this region, has been repeatedly implicated in other neurodevelopmental disorders and deletion of this gene specifically is thought to cause much of the neurologic symptoms characteristic of PMS." (PMID 30875393, 2019). "Phelan–McDermid syndrome is a neurodevelopmental disorder caused by the terminal deletion of chromosome 22 (22q13) followed by the loss of function of the SHANK3 gene." (PMID 27741506, 2016). "Though the gene SHANK3 is well-known susceptibility gene for neurodevelopmental disorders, there was only one report about the mutation screening of this gene in ID." (PMID 22509352, 2012). "Phelan–McDermid syndrome (PMS), also known as 22q13.3 deletion syndrome (OMIM #606232), is a rare neurodevelopmental disorder that can be caused by a terminal deletion or other rearrangement affecting the distal region of chromosome 22q, or pathogenic variants within the SHANK3 gene." (PMID 36833418, 2023). "In addition, our results also reinforce the need for the detailed LD mapping, mutation screening and CNV analysis of SHANK3 in different population or other neurodevelopmental disorders." (PMID 19566951, 2009). "Four of the 18 high confidence variants (in ERF, SETD1A, SHANK3 and ZBTB18) were recurrent, with these variants having been reported previously in individuals with neurodevelopmental disorders." (PMID 36117209, 2023). "In vivo studies in Shank3-KO mice showed severe behavioral abnormalities that are associated with ASD and related neurodevelopmental disorders, such as abnormal social behavior, impaired motor coordination, and repetitive self-injurious grooming." (PMID 36833418, 2023). "Haploinsufficiency of SHANK3 is widely recognized as the major cause of Phelan–McDermid syndrome (PMS), a complex neurodevelopmental disorder." (PMID 37528484, 2023).
neurodevelopmental disorder (continued). "In humans, SHANK3 gene (22q13.3) deletion triggers neurodevelopmental disorders like Phelan–McDermid syndrome (PMS), characterized by autistic like behaviors, hypotonia and delayed or absent speech." (PMID 36570823, 2022). "Considering SHANK3-ASD as a neurodevelopmental disorder, we studied postnatal day seven (P7), 21 (P21) and adult P140 mice." (PMID 35726031, 2022). "SHANK3 has been the focus of intense investigation because of its role in neurodevelopmental disorders such as ASD and PMS." (PMID 33568460, 2021). "This new rat model will help to further investigate the etiology and assess potential therapeutic target and strategy for Shank3-related neurodevelopmental disorders." (PMID 30971895, 2019). "The results highlight the importance of Shank3 in synaptic development and function and support a link between deficits in synapse function and neurodevelopmental disorders." (PMID 21167025, 2010). "Our results are consistent with altered synaptic development and function in Shank3 haploinsufficiency, highlighting the importance of Shank3 in synaptic function and supporting a link between deficits in synapse function and neurodevelopmental disorders." (PMID 21167025, 2010). "Together with prior behavioral evidence, this study establishes the Shank3Δe11-21 rat as a preclinical model for elucidating mechanisms of Shank3-related neurodevelopmental disorders and for evaluating potential early-life therapeutic interventions, including sleep-targeted strategies." (PMID 41667422, 2026). "Although less studied than SHANK3, SEZ6L2 has been implicated in neurodevelopmental disorders, and its dysregulation may contribute to the synaptic and behavioral abnormalities observed in ASD." (PMID 40330750, 2025). "However, it is important to note that the microdeletion deletes not only the FAM19A5 gene but also other neighboring genes, including SHANK3, which has been extensively studied in relation to neurodevelopmental disorders." (PMID 40763294, 2025). "Notably, the mRNA levels of ASD‐related risk genes like NLGN1, SHANK2, SHANK3, and CNTNAP2 are influenced by the prenatal suppression of histone deacetylase family, which are linked to neurodevelopmental disorders." (PMID 37807632, 2023). "An environmental model of neurodevelopmental disorders in which mice were exposed to maternal immune activation (MIA) during embryogenesis has been compared with mouse models that were genetically deficient for Cntnap2, Fmr1, or Shank3." (PMID 34065644, 2021). "Moreover, beyond a model for shankopathies, the isoform-specific Shank3 mouse model presented corresponds better in generic terms to a model for neurodevelopmental disorders with partly autistic behavior, which is mainly expressed by strong repetitive behavior." (PMID 36699652, 2022). "Shank3 is deleted in all reported cases of Phelan–McDermid syndrome (PMS), a neurodevelopmental disorder that is characterized by autistic-like behaviors." (PMID 35328799, 2022). "Our data indicate that, through their interaction at postsynaptic sites, Shank3 and δ-catenin contribute to a synaptic signalling pathway which is disrupted in ASD and other neurodevelopmental disorders." (PMID 33115499, 2020). "Our results, together with the recently reported beneficial effects of lithium in a Shank3-mutant mouse model of ASD and fragile X mouse models, suggest that lithium could have therapeutic potential for ASD and related neurodevelopmental disorders." (PMID 39633007, 2025).
neurodevelopmental disorder (continued). "To test whether SNR-derived organoids can be used to model genetic neurodevelopmental disorders, we generated CRISPR/Cas9-engineered PSC lines with partial homozygous or complete hemizygous SHANK3 deletions." (PMID 36202854, 2022). "Despite the importance of SHANK3 as a paradigmatic gene mediating neurodevelopmental disorders, its psychological effects in nonclinical populations have yet to be studied." (PMID 34188957, 2021).
neurological disorders (16 papers, 2014 to 2025). "Mutations or variations of SHANK3 are associated with various psychiatric and neurological disorders." (PMID 34504419, 2021). "Though not many cases have been observed, CTNND2 is somewhat similar to SHANK3 as alterations in both genes are associated with multiple neurological disorders." (PMID 33115499, 2020). "In a bunch of human neurological diseases, mutations on Shank3 or SAPAP are detected." (PMID 30626119, 2019). "Whether Shank3 downregulation is a direct cause or consequence of these neurological disorders, or an unrelated epiphenomenon remains open to question." (PMID 29321759, 2017). "The etiology of PMS is the deletion of the 22q13.3 gene segment, with SHANK3 being the primary contributor to nervous system disorders, including PMS." (PMID 40922359, 2025). "We chose this PMS dataset (a combination of patients with 22q13.33 microdeletion or SHANK3 sequence variants) to evaluate specificity of the AOA2 transcriptional signature in a neurological disease with no phenotypic overlap." (PMID 40413398, 2025). "However, it is still unclear to what extent SHANK3 deletions contribute to the PMS phenotype, and what other genes nearby are causal to the neurologic disease." (PMID 30875393, 2019). "SH3 and multiple ankyrin repeat domains protein 3 (Shank3) is one of the major scaffold proteins belonging to a family of higher order organizing molecules of the postsynaptic density and is involved in human neurological diseases." (PMID 30626119, 2019). "Current advances in SHANK3 protein research clearly correlate its deficit to a wide-range of human neurological disorders with developmental synaptic dysfunction that may also be associated with synaptic decline at later stages as observed in Alzheimer disease." (PMID 30643170, 2019). "Importantly, these experimental interpretations should remain be somewhat speculative as they are derived from preliminary studies, and more research is required to further clarify the significance of Shank3 deficits in other neurological disorders and experimental models." (PMID 29321759, 2017).
psychiatric disorder (15 papers, 2010 to 2025). A disorder characterized by behavioral and/or psychological abnormalities, often accompanied by physical symptoms. "In summary, this study can inform on the best endpoints and provides insights for patient stratification strategies for a future clinical study to explore vafidemstat actionability for SHANK3-associated psychiatric disorders." (PMID 40104333, 2025). "Taken together, these studies suggest that too little or too much Shank3 can contribute to the pathophysiology underlying these psychiatric disorders." (PMID 35266450, 2022). "Taken together, these studies suggest that too little or too much Shank3 is associated with several psychiatric disorders." (PMID 28477407, 2017). "If Shank3 mutations and CNVs are causally associated with these psychiatric disorders, cellular and circuit phenotypes should also be sensitive to Shank3 copy number." (PMID 28477407, 2017). "These 22q13 duplications involve multiple genes; consequently, the contribution of increased Shank3 to these psychiatric disorders was uncertain." (PMID 28477407, 2017). "These genetic studies suggest that decreased Shank3 function likely plays an important role in the pathophysiology of these psychiatric disorders." (PMID 28477407, 2017). "A parallel set of genetic studies suggest that increased Shank3 function also contributes to psychiatric diseases." (PMID 28477407, 2017). "A large body of work has analyzed SHANK3 in relation to psychiatric disorders and effects in animal models, but no previous study has examined the effects of variation in the gene within healthy, nonclinical human populations." (PMID 34188957, 2021).
brain disorder (12 papers, 2017 to 2023). A disease affecting the brain or part of the brain. "Numerous studies on the functions of Shank2 and Shank3, including those using mouse genetic approaches, have provided substantial insights into the mechanisms underlying Shank2- or Shank3-related brain disorders." (PMID 36311023, 2022). "Variants of the SH3 and multiple ankyrin repeat domains 3 (SHANK3), which encodes postsynaptic scaffolds, are associated with brain disorders." (PMID 33505245, 2020). "The mPFC has well-established roles in top-down regulatory control over various subcortical nuclei involved in regulating emotional, social, and cognitive behaviors, which are impaired in brain disorders associated with SHANK3 mutations." (PMID 30233305, 2018). "The brain region-specific Shank3 isoform expression and Shank3 interactome have been suggested to contribute to the phenotypic complexity and heterogeneity of SHANK3-associated brain disorders." (PMID 30233305, 2018). "Several mouse lines of knock-out, knock-in, overexpression, and viral knock-down for the Shank3 gene have been generated and characterized, which has provided important insights into the neuronal pathophysiology of SHANK3-associated brain disorders." (PMID 30482234, 2018). "A number of Shank3-mutant mouse lines have been generated and characterized in an effort to understand the in vivo functions of Shank3 and identify important mechanisms underlying Shank3-related brain disorders." (PMID 30356810, 2018). "Notably, beyond the synaptic changes, recent studies have suggested that Shank3 can also directly and indirectly affect gene expression in the nucleus, which may contribute to the neuronal pathophysiology of SHANK3-associated brain disorders." (PMID 31489248, 2019). "Genetic variants of the SH3 and multiple ankyrin repeat domains 3 (SHANK3) gene, which encodes excitatory postsynaptic core scaffolds cause numerous brain disorders." (PMID 31607862, 2019). "Our study provides evidence that Shank3 can form protein complexes in a brain region-specific manner, which further expands our understanding of the heterogeneity and complexity of SHANK3-related brain disorders." (PMID 28469556, 2017). "Both deletions and duplications of the SH3 and multiple ankyrin repeat domains 3 (SHANK3) gene, encoding excitatory postsynaptic scaffolds, are causally associated with various brain disorders, suggesting that proper Shank3 dosage is critical for normal brain development and function." (PMID 31489248, 2019). "More comprehensive and quantitative analysis of the Shank3 interactome in both physiological and pathological conditions will help us better understand its dynamic regulation and potential implications for various brain disorders." (PMID 28469556, 2017). "Considering the associations of GPR85/SREB2 with ASDs and SCZ, more investigations about the functional relationship between Shank3 and GPR85 would provide information on the detailed mechanisms of activity-dependent synaptic regulation and their potential implications in multiple brain disorders." (PMID 30233305, 2018).
cancer (7 papers, 2013 to 2025). A tumor composed of atypical neoplastic, often pleomorphic cells that invade other tissues. "SH3 and multiple ankyrin repeat domains 3 (SHANK3) has been implicated in inhibiting integrin function in cancer cells by binding to and sequestering active Rap1–GTP through its N-terminal SPN domain, thus limiting Rap1–GTP bioavailability at the plasma membrane." (PMID 39853211, 2025). "These SHANK3 driven processes could contribute to cancer progression and metastasis, but they could also support proper seeding and maturation and release of hematopoietic stem cells from the bone marrow niche." (PMID 31321035, 2019). "In conclusion, the specific ablation of TAU, Shank3, and GPX4, along with utilizing MWA technology, presents new opportunities for studying ND and cancer induced by ferroptosis." (PMID 38962561, 2024). "About five-fold more cancer samples exhibit SHANK2 amplification compared to SHANK1 and SHANK3." (PMID 32661924, 2021). "Importantly, target genes involved in epithelium development (RGMA, SHANK3, PAX6, PFN1, WNT4) and cancer (CBL, CYCS, FGF7, IGF1R, PTEN, PIK3CD, WNT4) address to a further role in the onset of epithelial abnormalities and oncogenesis." (PMID 23936163, 2013).
infection (3 papers, 2015 to 2025). The state of being infected such as from the introduction of a foreign agent such as serum, vaccine, antigenic substance or organism. "Consistent with our results from the luciferase assays, infection of the virus expressing miR-504 decreased Shank3 proteins in cultured hippocampal neurons confirmed by western blot experiments." (PMID 26572867, 2015). "SHANK3 variants are associated with an increased risk of psychiatric abnormalities and regression, raising the question of whether the deterioration in the present case occurred as a consequence of an acute incident (such as infection or antibody-negative AE or whether it was inherent to PMS." (PMID 41282476, 2025). "A comparison of the synaptosomal protein composition revealed distinct changes upon infection, with multiple proteins such as EAAT2, Shank3, AMPA receptor, and NMDA receptor subunits being downregulated, whereas inflammation-related proteins showed an upregulation." (PMID 30068357, 2018).
tumor (2 papers, 2016 to 2020). "These include some examples of genes that were hypo-methylated and up-regulated during the transition from KSHV (+) cell to KSHV (+) tumor and are now hyper-methylated and down-regulated, such as Angpt4, Pdgfb, and Shank3." (PMID 32603362, 2020). "The median relative quantification ratios between normal and tumor varied from 1.90 (IFNAR2–IL10RB) to 7.78 (SHANK3–ACR)." (PMID 27058892, 2016).
chromosomal disorder (1 paper, 2016). Clinical conditions caused by an abnormal chromosome constitution in which there is extra or missing chromosome material (either a whole chromosome or a chromosome segment). "Our study shows that cognitive, motor and especially language development are significantly impaired in all children with 22q13.3 deletion syndrome including SHANK3 as compared to children with more common chromosomal disorders." (PMID 27118998, 2016).
immune dysfunction (1 paper, 2013). "Previous case reports have also suggested a link between immune dysfunction and SHANK3 deficiency." (PMID 23758760, 2013).
renal disorders (1 paper, 2022). "SHANK3 is unlikely to be associated with renal phenotypes as no cases of renal disorders were observed in a large study of PMS caused by SHANK3 pathogenic variants or SHANK3 microdeletions." (PMID 35741804, 2022). "SHANK3 is the primary gene associated with neurobehavioral features of PMS but was not in the region associated with kidney disorders in this investigation." (PMID 35741804, 2022). "It is unlikely to be associated with kidney disorders based on the lack of renal disorders observed in individuals with the smallest 22q13.3 terminal deletions or carrying SHANK3 pathogenic variants." (PMID 35741804, 2022).
retinopathy (1 paper, 2023). "The SHANK3 gene, expressed in the brain, has also been associated to fibrinogen levels and platelet count, which has been reported to be risk factors in the development and progression of retinopathy." (PMID 37033211, 2023).